ATF3 (activating transcription factor 3)
Diseases named in the same sentence as ATF3 in open-access papers (continued):
Sharing a sentence is not in itself a finding about the gene and the disease.
melanoma (36 papers, 2011 to 2026). A malignant, usually aggressive tumor composed of atypical, neoplastic melanocytes. "In melanoma, the transcription repressor ATF3 induced by the Wnt/ß-catenin pathway has been associated with CCL4 repression." (PMID 39008536, 2024). "ATF3 is also expressed in human dermis, but hardly anything is known about its function in human dermal fibroblasts (HDFs) or melanoma-associated fibroblasts." (PMID 32373541, 2020). "HDFs expressing high levels of ATF3 suppressed the growth and migration of melanoma cells in association with downregulation of different cytokines including IL-6 in vitro." (PMID 32373541, 2020). "Supporting their role as tumor suppressors, low expression of NDRG1_pT346 or ATF3 was associated with a significant decrease in survival of patients in the TCGA melanoma dataset." (PMID 26304929, 2015). "High levels of ATF3 expression have also been shown to inhibit melanoma cell growth, cell migration, and tumor development, further supporting our findings." (PMID 40699755, 2025). "To validate the functional significance of the P38/MAPK/ATF3/IL-24 axis in vivo, we established melanoma xenograft models with stable knockdown of ATF3 or IL-24." (PMID 40866941, 2025). "In skin cancer models, ATF3 negatively regulates CAF activation, and in melanoma models, ATF3 overexpression in fibroblasts has an anti-tumour effect on growth and migration." (PMID 41198649, 2025). "Melanoma cells have a well-defined stressed cell state, which is marked by the upregulation of immediate early transcription factors (JUN, FOS, ATF3, NR4A1, DUSP) linked to melanoma oncogenic programs, inflammation, and stress response." (PMID 36765834, 2023). "Specifically, increased calcium influx triggered the nuclear translocation of NFATc1, which subsequently downregulated the transcription factor ATF3, leading to melanoma apoptosis." (PMID 37198657, 2023). "Increased calcium influx triggered the nuclear translocation of NFATc1, subsequently downregulated the transcription factor ATF3, and consequently led to melanoma apoptosis." (PMID 37198657, 2023). "We also turned to TCGA SKCM database to investigate the clinical implications of ATF3 in melanoma and the relationship between ATF3 expression and ferroptosis and antitumor immunity." (PMID 35738798, 2022). "More importantly, high expression of ATF3 significantly correlated with better survival of patients with melanoma." (PMID 35738798, 2022). "Activated transcription factor 3 (ATF3) expression is induced by β-catenin in melanoma cells, which suppresses C-C motif chemokine ligand 4 (CCL4) gene transcription." (PMID 36232859, 2022). "We then employed immunohistochemical staining of TMA consisting of 82 melanoma tissues to analyze the relationship between ATF3 and ferroptosis indicator PTGS2, which revealed a significant positive correlation between the staining scores of them." (PMID 35738798, 2022). "Recently we reported that ATF3 suppresses expression of the cytokine IL-6 in dermal fibroblasts to inhibit melanoma cell growth through paracrine pathways." (PMID 33539340, 2021). "IL-6, a pro-inflammatory cytokine, has been well-documented to play important roles in development and progression of melanoma, and its expression was markedly reduced in ATF3-overexpressing HDFs." (PMID 32373541, 2020). "We found that addition of rhIL-6 to CM from ATF3-overexpressing HDFs reversed the inhibitory effect of the CM on proliferation of melanoma cells and restored the colony growth of both UACC62 and Mel-JuSo cells to control levels." (PMID 32373541, 2020). "The in vivo inhibitory effects of HDFs with high expression of ATF3 on melanoma formation and growth suggests a potential new approach for treatment of melanoma in the clinic, namely inducing tumor stromal cells to increase ATF3 expression." (PMID 32373541, 2020).
melanoma (continued). "Taken together, these data suggest that overexpression of ATF3 in HDFs decreases the secretion of soluble factors that play crucial roles in melanoma cell growth and migration." (PMID 32373541, 2020). "Taken together, these data suggest that suppression of IL-6 expression plays a crucial role in the inhibitory effect of ATF3-overexpressing HDFs on melanoma cell proliferation and migration." (PMID 32373541, 2020). "Our present study revealed that ATF3 expression is low in stromal cells of clinical melanoma tissues, and human dermal fibroblasts with overexpression of ATF3 can inhibit melanoma cell growth and migration both in culture and in vivo in a mouse model." (PMID 32373541, 2020). "Taken together, these data suggest that decreased production of IL-6 in ATF3-overexpressing HDFs contributes to inhibition of melanoma cell proliferation and migration by blocking the STAT3 pathway." (PMID 32373541, 2020). "Next, we investigated the effects of ATF3 overexpression in fibroblasts on melanoma function in vitro." (PMID 32373541, 2020). "We also observed strong nuclear staining of ATF3 in melanoma tumor cells, and we are investigating the role of intratumoral ATF3 in melanoma growth and progression in a separate study." (PMID 32373541, 2020). "In agreement with the previous studies, we found that phosphorylation of STAT3 in both Mel-JuSo and UACC62 melanoma cells decreased dramatically after culture with CM derived from ATF3-overexpressing HDFs." (PMID 32373541, 2020). "More importantly, HDFs pretreated with cyclosporine A or phenformin to induce ATF3 expression inhibited melanoma cell growth in vitro and in vivo." (PMID 32373541, 2020). "A co-culture assay shows that the numbers of Mel-JuSo and UACC62 melanoma cells co-cultured with ATF3-overexpressing HDFs were significantly less than the numbers of melanoma cells co-cultured with control HDFs." (PMID 32373541, 2020). "Both Mel-JuSo and UACC62 melanoma cells migrated significantly less when co-cultured with ATF3-overexpressing HDFs than when co-cultured with NEO-expressing HDFs." (PMID 32373541, 2020). "Adding recombinant IL-6 to melanoma cells reversed those in vitro and in vivo effects, suggesting that ATF3 expression by HDFs regulates melanoma progression through the IL-6/STAT3 pathway." (PMID 32373541, 2020). "In summary, our study reveals that ATF3 suppresses human melanoma growth and that inducing the expression of ATF3 in HDFs can inhibit melanoma growth, a new potential melanoma therapeutic approach." (PMID 32373541, 2020). "In melanoma cells, b-catenin translocation to the nucleus upregulates ATF3, which blocks the promoter of CCL44." (PMID 30926812, 2019). "Electrophoretic mobility shift assay demonstrated increased DNA‐binding activity of ATF‐3 in response of melanoma cells to imiquimod treatment." (PMID 26578344, 2016). "To determine whether Vin upregulates IL-24 expression through the P38/MAPK/ATF3 signaling pathway, we treated melanoma cells with the P38 inhibitor SB203580 in combination with Vin." (PMID 40866941, 2025). "However, in melanoma and non-small cell lung cancer, ATF3 has a pro-tumour role by promoting expression of PD-1L, which enables tumour cells to evade cytotoxic T-cells." (PMID 41198649, 2025). "Together, these results indicate that ATF3 may act as a key transcriptional regulator linking P38 activation to IL-24 upregulation, thereby contributing to the anti-melanoma effects of Vin." (PMID 40866941, 2025). "Moreover, it activates the P38/MAPK/ATF3 signaling pathway to stimulate IL-24 secretion by melanoma cells, which contributes to reshaping the immunosuppressive TME and enhancing CD8+ T cell-mediated immune responses." (PMID 40866941, 2025). "In addition, ATF3 knockdown was found to prominently abolish the upregulation of miR-21–3p in melanoma cells after either monotreatment with RSL3 or combined with IFN-γ." (PMID 35738798, 2022).
melanoma (continued). "Furthermore, the investigators found that the Wnt signaling target gene ATF3–which also binds at the promoter region of the CCL4 gene—was expressed at higher levels in the β-catenin activated melanoma tumors." (PMID 33672668, 2021). "Then, we tested the effects of ATF3 overexpression in HDFs on melanoma cell migration." (PMID 32373541, 2020). "To investigate whether induction of ATF3 expression in HDFs could inhibit melanoma cell growth, we pretreated HDFs with either CsA or phenformin, then removed the drugs and continued culturing the HDFs with complete growth medium." (PMID 32373541, 2020). "In addition, a cell colony assay showed that CM derived from ATF3-overexpressing HDFs inhibited colonic growth of melanoma cells significantly." (PMID 32373541, 2020). "Finally, both cell migration and wound healing assays showed that addition of rhIL-6 blocked the inhibitory effects of CM from ATF3-overexpressing HDFs on melanoma cell migration." (PMID 32373541, 2020). "We found that the addition of recombinant human IL-6 protein in vitro and in vivo could reverse the inhibition of melanoma cell growth and migration by ATF3-overexpressing HDFs." (PMID 32373541, 2020). "To further support this hypothesis, we grew melanoma cells in conditioned medium (CM) collected from cultures of ATF3-overexpressing HDFs." (PMID 32373541, 2020). "Activating transcription factor 3 (ATF3) plays a crucial role in regulating tumorigenesis and development, but whether the expression of ATF3 in human dermal fibroblasts (HDFs) can affect melanoma development hasn't been studied." (PMID 32373541, 2020). "Our results show that ATF3 expression is downregulated in stromal cells of human melanoma." (PMID 32373541, 2020). "Taken together, these data suggest that compounds capable of inducing ATF3 expression in HDFs could potentially offer a novel treatment strategy for melanoma in vivo." (PMID 32373541, 2020). "Interestingly, the AM404 + GSK126 combination led also to upregulation of ATF3, a candidate melanoma tumor suppressor, as evaluated at 18 h." (PMID 30710146, 2019). "Furthermore, pre‐treatment of melanoma cells with the inhibitor of IRE1α (irestatin) blocked imiquimod‐induced ATF‐3." (PMID 26578344, 2016). "TCA cycle, a critical metabolic pathway underlying tumor cell metabolism for energy production to the cell, is reported to be a novel immune checkpoint blockade as inhibiting it could improve the anti-PD-1 immunotherapy efficacy in melanoma cells via ATF3-mediated PD-L1 expression and glycolysis." (PMID 38664705, 2024). "Therefore, we could conclude that the inhibitory effect of ATF3-overexpressing HDFs on melanoma cell growth and migration is mainly through the IL-6/STAT3 pathway." (PMID 32373541, 2020). "Our study provides an opportunity to develop a novel strategy for melanoma treatment, to specifically induce ATF3 expression in tumor stromal cells, which could be combined with other conventional and/or innovative treatments to enhance melanoma therapy in the future." (PMID 32373541, 2020). "Therefore, the present study aims to investigate whether the expression level of ATF3 in dermal fibroblasts can affect melanoma cell growth and migration." (PMID 32373541, 2020). "However, we cannot discount that the reductions of other cytokines including IL-8, SDF-1 and COX-1/2 in ATF3-overexpressing HDFs could also contribute to the inhibition of melanoma growth and migration." (PMID 32373541, 2020). "Therefore, we tested whether replenishment of IL-6 could counteract the effects of ATF3-overexpressing HDFs on melanoma cell growth and migration." (PMID 32373541, 2020). "Thus, it is likely that the decreased production of cytokines in HDFs overexpressing ATF3 may be critical for the inhibition of melanoma cell growth and migration." (PMID 32373541, 2020).
melanoma (continued). "Repression of multiple cytokine/chemokine encoding genes might be related to the large induction of ATF3 by both drugs and might possibly parallel non-cell-autonomous events of chemokines in melanoma." (PMID 27973612, 2016). "Key targets of SAG treatment for melanoma are enriched in the phosphatidylinositol 3-kinase/AKT pathway 42, and activating transcription factor-3 inhibits melanoma growth by downregulating the extracellular regulated protein kinase and AKT levels." (PMID 39744474, 2025). "Wnt/β-catenin can induce the expression of activating transcription factor 3 (ATF3), resulting in the reduction of CCL4 in a mouse model of melanoma." (PMID 36672698, 2023). "The relative expression level of the hub genes was reverified in melanoma cell lines, and showed that HIF1A, IL1B, HMOX1, MMP3, CDKN2A and TIMP1 were upregulated, while PTEN, PRKCA, ATF3 and BRAF were downregulated in melanoma samples." (PMID 36226170, 2022). "Taken together, these results demonstrated the crucial role of ATF3 in promoting miR-21–3p upregulation in IFN-γ-potentiated ferroptosis and its implication in melanoma pathogenesis and anti-PD-1 immunotherapy." (PMID 35738798, 2022). "For the level of mRNA expression in the TCGA database and melanoma cell lines, SLC39A14, PSMB4, CRELD2, CDKN2A and TIMP1 were higher in SKCM tissues than in normal skin tissues, and NDRG1, ATF3, and JUND had an opposite trend." (PMID 36226170, 2022). "This negative feedback was substantiated by then demonstrating that gene knockdown of ATF3 and CTNNB1 in melanoma cell lines led to upregulation of CCL4 expression." (PMID 33672668, 2021). "Along with FOXD1 and ATF3, CREB5 formed a transcription factor regulatory network that negatively regulates MAPK signalling, which is suppressed by FZD3 in melanoma." (PMID 32843066, 2020). "Our co-culture and conditioned medium assays demonstrated that ATF3-overexpressing HDFs blocked both Mel-JuSo and UACC62 melanoma cell proliferation and migration through a paracrine signaling pathway." (PMID 32373541, 2020). "The importance of ATF3 and NDGR1 as tumor suppressors in melanoma was supported by the analysis of melanoma patient survival data in the TCGA that low levels of these genes were associated with poor survival." (PMID 26304929, 2015). "When the expression of CD146 was rescued in CD146–knockdown melanoma cells, Id-1 expression was increased, and ATF-3 expression was reduced, which showed that both Id-1 and ATF-3 were specifically regulated by CD146." (PMID 25685061, 2015). "For example, ATF3 acts as a transcriptional activator of PD‐L1 expression; its inhibition led to decreased PD‐L1 levels and enhanced the population of activated tumour‐infiltrating CD8+ T cells in melanoma models." (PMID 41521078, 2026). "Indeed, CM from ATF3-overexpressing HDFs inhibited migration of both Mel-JuSo and UACC62 melanoma cells compared with CM from NEO-expressing HDFs, which was further confirmed by a scratch migration assay." (PMID 32373541, 2020). "We observed in benign nevi and normal skin tissues that vimentin-expressing stromal cells expressed ATF3 (stained red, white arrow heads), while the majority of vimentin+ cells in malignant melanoma did not express detectable ATF3 (white arrows)." (PMID 32373541, 2020). "These in vivo experiments validated our in vitro findings by showing that HDFs with high expression of ATF3 can repress melanoma cell tumor formation and growth, probably through negative regulation of IL-6 production." (PMID 32373541, 2020). "Interestingly, other signaling pathways including the NF-κB, PI3K/AKT, and MAPK pathways, were not altered in the melanoma cells cultured with CM from ATF3-overexpressing HDFs." (PMID 32373541, 2020).
melanoma (continued). "Tumor cells identified by positive S100 staining (black arrows) expressed clearly detectable amounts of ATF3 (black arrows), while melanoma stromal cells identified by their spindle shapes and absence of S100 protein displayed extremely weak ATF3 staining (red arrows)." (PMID 32373541, 2020). "Interestingly, we found that only IL-6 and IL-8 expression increased significantly after ATF3 deletion, which could also explain why the ATF3 knockout HDFs did not have a significant effect on melanoma cell growth and migration." (PMID 32373541, 2020). "Mechanistically, c-MYC has been reported to mediate PI induction of NOXA in melanoma cells, whereas NOXA transcription can also be regulated by ATF3/ATF4 in the non-PI setting through a variety of signaling pathways, including the endoplasmic reticulum stress pathway." (PMID 39302104, 2024). "Co-culture of ATF3-deleted HDFs with Mel-JuSo or UACC62 melanoma cells did not affect melanoma cell growth or migration, suggesting that endogenous ATF3 levels in in vitro cultured HDFs are insufficient to affect melanoma growth or migration significantly." (PMID 32373541, 2020).